PRR29 (proline rich 29)
Synonyms: C17orf72; FLJ11724; DKFZp761M2312
Tractability: No criterion of Open Targets' tractability assessment is met for any kind of drug.
Gene: Protein-coding gene on chromosome 17 (63,998,351 to 64,004,305, forward strand). Ensembl gene ENSG00000224383.
Subcellular location (Human Protein Atlas): Nucleoli
Genetic constraint (gnomAD): Loss-of-function variants: 19 observed, 21.59 expected, observed/expected ratio (o/e) 0.88, 90% interval 0.61 to 1.29. The upper end of that interval is the gene's LOEUF score, 1.29, which puts it in group 5 of 6, group 1 being the genes least tolerant of losing a copy. Missense variants: 218 observed, 219.81 expected, observed/expected ratio (o/e) 0.99, 90% interval 0.89 to 1.11. Synonymous variants: 105 observed, 93.28 expected, observed/expected ratio (o/e) 1.13, 90% interval 0.96 to 1.32.
Homologues: Orthologues: macaque PRR29 (87% identical), chimpanzee PRR29 (86% identical), pig PRR29 (70% identical), rabbit PRR29 (69% identical), dog PRR29 (67% identical), guinea pig PRR29 (67% identical), rat Prr29 (63% identical), mouse Prr29 (50% identical).
Diseases named in the same sentence as PRR29 in open-access papers:
PRR29 is named in the same sentence as 1 disease in open-access papers, as found by Europe PMC text mining. Sharing a sentence is not in itself a finding about the gene and the disease.
PRR29 shares sentences with these, for which no sentence is quoted: breast carcinoma (1 paper).